SETDB1 (SET domain bifurcated histone lysine methyltransferase 1)
Diseases named in the same sentence as SETDB1 in open-access papers (continued):
Sharing a sentence is not in itself a finding about the gene and the disease.
tumor (continued). "An increasing number of observations indicate SETDB1 involvement in tumor initiation and progression, the antitumor immune response, and gene expression control." (PMID 39519018, 2024). "SETDB1 has been previously identified as an epigenetic checkpoint that suppresses tumor-intrinsic immunogenicity by repressing latent transposable element (TE)-derived regulatory elements." (PMID 39768193, 2024). "Further biochemical and cellular experiments are needed to clarify how PHF8 maintains the stability of nuclear SETDB1 and further regulates its dynamic activity in tumor cells." (PMID 37454216, 2023). "Our findings have demonstrated that both MCT1 K473 tri‐methylation and SETDB1 can promote tumor glycolysis and M2‐like polarization of TAMs." (PMID 37541664, 2023). "Co-administration of CDK4/6 inhibitor palbociclib obviously enhanced the therapeutic efficacy of SETDB1 depletion on tumor growth by protecting TRIM28-mediated p-RB from proteasomal degradation both in vitro and in vivo." (PMID 38057834, 2023). "This discovery suggests that SETDB1‐mediated tri‐methylation at K473 is a vital regulatory mechanism for lactate shuttle and tumor progression." (PMID 37541664, 2023). "Multiple studies have demonstrated that the methyltransferase SETDB1 is up‐regulated in CRC and is associated with higher histological grades and Tumor‐Node‐Metastasis (TNM) staging." (PMID 37220590, 2023). "In keeping with these findings, the hypoxia-induced increase of SETDB1 protein suggests an oncogenic function in an oxygen-limited tumor microenvironment (TME)." (PMID 37850636, 2023). "In summary, our findings suggest that PHF8 facilitates SETDB1 stabilization to establish H3K9me3 marks on heterochromatin, leading to retrotransposon silencing and tumor immune evasion." (PMID 37454216, 2023). "In summary, our data suggest that MCT1 K473 tri‐methylation is necessary for SETDB1‐mediated tumor glycolysis and M2‐like polarization of TAMs." (PMID 37541664, 2023). "The results indicated that silencing of SETDB1 limited tumor cell proliferation and the infiltration of tumor cells by T cells via FOSB/miR-22/BATF3/PD-L1 axis and consequently arresting tumor cell immune evasion." (PMID 35497876, 2022). "In order to further explore the expression levels of SETDB1 in different tumor tissues and paracancerous tissues, we further performed the differential expression analysis using several online databases." (PMID 35656340, 2022). "In this process, SETDB1 deficiency plays an essential role in decreasing H3K9me3 deposition on the chromosomes encoding ERV-derived antigens and up-regulating tumour immunogenicity." (PMID 36582533, 2022). "As an important player in tumor epigenetics, SETDB1 expression is significantly differential in most cancerous tissues and adjacent healthy tissues, which is consistent with our findings." (PMID 35656340, 2022). "This is mainly attributed to H3K9me3 deposition by SETDB1 on tumour-suppressive genes, retrotransposons, and immune clusters." (PMID 36582533, 2022). "With respect to cancer, KZNF proteins, as well as TRIM28 and SETDB1, have been shown to exert pleiotropic roles as oncogenes or tumor suppressors in different tumor types." (PMID 35162997, 2022). "SETDB1 is an important oncogene involved in tumorigenesis and tumor progression through different biological mechanisms." (PMID 35656340, 2022). "We also observed that the expression levels of SETDB1 were significantly lower in the stage 4 tumor than those in early-stage tumors." (PMID 35656340, 2022). "Here, we review the effects of SETDB1 on tumourigenesis and progression, particularly its role in regulating the tumour immune response, and present the current challenges and future perspectives of antitumour therapy targeting SETDB1." (PMID 36582533, 2022). "Given the important role of SETDB1 in tumor immune evasion, this provides new ideas and directions for targeting SETDB1." (PMID 36077559, 2022).
tumor (continued). "The silencing of SETDB1 reactivates the expression of immune stimulatory genes and triggers an anti-tumor cytotoxic T-cell response in a murine model." (PMID 36011043, 2022). "Mechanically, elevated SETDB1 facilitates H3K9 methylation at the promoter regions of multiple tumour-suppressive genes, leading to gene silencing and tumourigenesis." (PMID 36582533, 2022). "SETDB1-mediated hyperactivation of Akt was identified to promote tumor development in non-small-cell lung carcinoma (NSCLC)." (PMID 35159180, 2022). "Overall, SETDB1 amplification is closely correlated with poor prognosis of multiple malignancies and contributes to tumourigenesis, tumour progression and immune evasion." (PMID 36582533, 2022). "Through immunohistochemical experiments, we verified that the TRAF4 expression in subcutaneous tumor tissue decreased, and the SETDB1 expression were also decreased in accordance with TRAF4, which were consistent with previous cell experiments." (PMID 36077559, 2022). "On the other hand, SETDB1 in tumor cells forms a complex with TRIM28 or acts together with KDM5B that interferes with PD-L1 expression by blocking double-stranded RNA (dsRNA) production through the endogenous retroviral (ERV) pathway." (PMID 36713412, 2022). "SETDB1 plays an important role in tumor progression, participates in many tumor processes, and is a potential target for tumor therapy." (PMID 36077559, 2022). "The results showed that SETDB1 was highly expressed in tumor tissues and rarely expressed in normal tissues." (PMID 35656340, 2022). "Recently, two studies published in Nature systematically revealed the effects of and mechanisms behind SETDB1 regulation of tumour-intrinsic immunogenicity." (PMID 36582533, 2022). "Further studies are required to clarify potential context-specific functions of SETDB1 in promoting tumor cell survival." (PMID 35602594, 2022). "SETDB1 expression is upregulated in LIHC tissues and is associated with tumor size, enhanced stage, and TNM classification." (PMID 35656340, 2022). "LINC00476 acts as a tumour suppressor by downregulating SETDB1 to inhibit proliferation, invasion, and migration in NSCLC." (PMID 34299035, 2021). "On the other hand, in invasive tumor cells undergoing TGF-β-induced EMT, repression of SETDB1 causes de-repression of the Snail promoter." (PMID 33803458, 2021). "For example, SETDB1 positively stimulated the WNT-β-catenin pathway to play a role in increasing tumour growth and promoting transformation in NSCLC cells." (PMID 34299035, 2021). "In non-invasive tumor cells, TGF-β favors the association of methyltransferase SETDB1 with Smad3 which mediates H3K9me in the Snail promoter, repressing its expression." (PMID 33803458, 2021). "When it comes to tumorigenesis, SETDB1 downregulates important tumor suppressor genes through histone methylation, acting primarily as an oncogene but also rarely as a tumor suppressor." (PMID 34440561, 2021). "In the non-invasive tumor mass, TGF-β induces the association of SETDB1 with Smad3 to repress the expression of Snail through mediating H3K9 methylation in the promoter of Snail." (PMID 32114978, 2020). "In current study, we also discovered that the classic tumor suppressor genes p21 is a target gene of SETDB1." (PMID 32393761, 2020). "SETDB1 is instead a gatekeeper of tumor survival whose chromatin remodeler role is recently emerged as a potential therapeutic target for immunotherapy to avoid leukemic cells evasion from immune system." (PMID 32471360, 2020). "In another study, SETDB1 overexpression was proposed to be a prognostic marker to predict tumor recurrence in patients with early stage NSCLC." (PMID 33343623, 2020). "It was shown that SETDB1 and DNMT3a directly interact and localize at the promoter regions of tumor suppressors and induce heterochromatin formation and gene silencing." (PMID 31405032, 2019).
tumor (continued). "Conversely, SETDB1 has also been found to silence the oncogene ANXA2 to achieve tumour-suppressor roles such as suppressing distal metastasis in lung cancers." (PMID 30850015, 2019). "At later stages, SETDB1 becomes dispensable for tumor progression and its expression diminishes, though it remains high compared to normal lung epithelial cells." (PMID 31398867, 2019). "These paradoxical findings suggest that SETDB1 can act as a proto-oncogene or tumour suppressor depending on the cellular context." (PMID 30850015, 2019). "Compared to the control, the size of tumor increased significantly when HCC cells were subjected to an overexpression of SETDB1 in vivo." (PMID 29739365, 2018). "Silence of SETDB1 was found to inhibit lung tumor growth in vitro and in vivo, while it upregulation promoted the tumor invasiveness, highlighting its role as a novel therapeutic target." (PMID 30309377, 2018). "This indicates that loss of SETDB1 and WDE in germ cells blocks differentiation, giving rise to a tumor phenotype." (PMID 30297796, 2018). "Increased expression of SETDB1 promotes tumor invasiveness and sensitizes anti-tumor growth by mithramycin, a SETDB1 and Sp1 inhibitor." (PMID 26824986, 2016). "To explore genetic aberrations associated with SETDB1 amplification and/or overexpression, we profiled 84 Asian HCC primary tumour tissue samples with exome sequencing, Human SNP array 6.0 and RNA expression microarrays." (PMID 26471002, 2015). "Together, our data suggest that SETDB1 inhibition leads to suppressed tumour growth and increased cell differentiation in HCCLM3 xenograft models." (PMID 26471002, 2015). "We found that SETDB1 was highly expressed in tumour tissues relative to the adjacent normal controls." (PMID 26471002, 2015). "In the doxycycline-treated, SETDB1 knocked down group (n=4), in addition to an increased abundance of trabeculae and nests, the tumour cells also formed a gland-like structure." (PMID 26471002, 2015). "SETDB1 knockdown efficiency was confirmed using RT–qPCR, western blot and IHC analyses using the tumour samples taken from the end of study." (PMID 26471002, 2015). "We identified specific H3K4 and H3K9 methyltransferases, such as Mll, Mll3, Setd1a, Ehmt2, Suv39h1, and Setdb1 as biomarkers of residual tumor cells persisting after chemotherapy." (PMID 23520493, 2013). "Mechanistically, SETDB1 contributes to this resistance by epigenetically repressing ERVs and interferon‐stimulated genes, thereby dampening type I interferon signaling and reducing tumor immunogenicity." (PMID 41493679, 2026). "However, some potential biomarkers still remain unexplored, like SETDB1, a histone methyltransferase involved in epigenetic silencing of tumor suppressor genes." (PMID 41503337, 2025). "In mouse tumor models, loss of SETDB1 results in expression of ERV sequences, which induce ERV-derived type I IFN responses, which associates with enhanced lymphocyte infiltration, reduced tumor growth, and enhanced responsiveness to radiotherapy." (PMID 40387511, 2025). "Targeting histone methyltransferases involved in these R-loop-mediated epigenetic changes, such as G9a/GLP and SETDB1, could enhance the anti-tumor effects of BOLD-100." (PMID 40514666, 2025). "In addition, current analyses show a correlation between SETDB1 presence, DNA methylation levels of epigenomic targets, tumor aggressiveness, and response to treatments." (PMID 39945463, 2025). "The results suggest that SETDB1 may promote tumor invasion and migration and help the tumor cells escape from immune surveillance through cell–cell adhesion and interaction-related biological processes." (PMID 39768193, 2024). "Interestingly, a related histone methyltransferase SETDB1 was recently demonstrated to play a role in anti-tumor immunity by regulating expression of endogenous retroelements." (PMID 38653864, 2024). "In tumorigenesis, SETDB1 downregulates the expression of tumour suppressor factors in most cases." (PMID 38317200, 2024).
tumor (continued). "Thereby, tumor burden decreased after Setdb1 KO in immunocompetent mice." (PMID 39519018, 2024). "Finally, in HCCLM3 xenotransplantation models in nude mice, SETDB1 knockdown significantly inhibited tumor growth and increased cell differentiation." (PMID 39583200, 2024). "SETDB1 is a H3K9 methyltransferase and is associated with immune cell function and tumour immunity." (PMID 38317200, 2024). "Importantly, SETDB1 can suppress tumor innate immunogenicity and evade immune responses by inhibiting transposable elements enriched genomic regions." (PMID 39583200, 2024). "CRISPR/Cas9-mediated KO of Setdb1 or its interacting partner Atf7ip (activating transcription factor 7-interacting protein) in multiple murine tumor models increased antigen expression and resulted in retardation of tumor growth in immunocompetent mice." (PMID 39519018, 2024). "A regulator of SETDB1 maintenance, PHF8, has been identified as a mediator of tumor immune escape; its ablation stimulates antiviral mimicry in colorectal cancer cells, resulting in the inhibition of tumor growth and immune susceptibility." (PMID 39205286, 2024). "SETDB1 expression was elevated in 4 of 6 pairs of tumor tissues compared with control tissues." (PMID 39583200, 2024). "In conclusion, SETDB1 can act as a transcription factor and promote gene expression in tumours." (PMID 38317200, 2024). "Less commonly, SETDB1 inhibits tumour progression, depending on the stage and type of the tumour." (PMID 38317200, 2024). "Therefore, SETDB1 inhibits tumour immunity in OC, and the function of SETDB1 in the immune system of OC needs to be further elucidated." (PMID 38317200, 2024). "In addition, SETDB1 is functionally involved in different aspects of tumorigenesis, including suppressive anti-tumor immunity." (PMID 37850636, 2023). "Furthermore, the disruption of either SETDB1 or ATF7IP in tumor cells restores tumor antigen expression and augments tumor immunogenicity." (PMID 38057834, 2023). "While the role of SETDB1 in tumors has not been completely delineated, most studies suggest that SETDB1 has prooncogenic potential by regulating key tumor-associated genes." (PMID 35372573, 2022). "H3K9me3 mediated by SETDB1 contributes to the repression of developmental genes that maintain cells in an undifferentiated state, an important component for the metastatic potential of tumor cells." (PMID 36011043, 2022). "In addition, a recent in vivo IO CRISPR screen in mouse tumors identified SETDB1 as a suppressor of intrinsic tumor immunogenicity." (PMID 35602594, 2022). "Finally, we demonstrated that PELP1 plays a critical role in SETDB1 mediated tumor progression in vivo." (PMID 35395812, 2022). "SETDB1 could also inhibit T cell cytotoxicity and promote tumor growth and immune cell infiltration via the FOSB/miR-22/BATF3/PD-L1 axis." (PMID 35497876, 2022). "We found that SETDB1 was significantly related to the specific tumor-infiltrating immune cell populations and expression of clinically targetable immune checkpoints and may be a promising immunotherapy target." (PMID 35656340, 2022). "Interestingly, knockdown of PELP1 in SETDB1 overexpression (MCF7-PELP1KD + SETDB1) xenografts resulted in significantly reduced tumor growth compared to MCF7-SETDB1 xenografts, suggesting that PELP1 KD effectively reduces SETDB1 mediated tumor progression." (PMID 35395812, 2022). "We first confirmed that SETDB1 was widely expressed in human normal and tumor tissues." (PMID 35656340, 2022). "Thus, the pharmacological targeting of SETDB1 can increase the tumor cell response to immunotherapies." (PMID 36011043, 2022). "Furthermore, SETDB1 silencing promoted the T cell-mediated cytotoxicity to tumor cells via the FOSB/miR-22/BATF3/PD-L1 axis and hindered CRC tumor growth in mice while leading to decreased immune cell infiltration." (PMID 35497876, 2022).
tumor (continued). "Similarly, for TCGA-LIHC patients, we observed that the expression level of SETDB1 is significantly elevated in tumor tissues compared to that in paracancerous tissues." (PMID 35656340, 2022). "Our results, taken together with previous reports, suggest that SETDB1 may affect various aspects of tumour progression such as cell division and cell migration, at multiple levels by different mechanisms." (PMID 36330589, 2022). "Additionally, the protein expression of SETDB1, BATF3, and PD-L1 was diminished while FOSB expression was upregulated in the presence of sh-SETDB1+OE-NC while opposite results were detected in the tumor tissues of mice treated with sh-SETDB1+OE-BATF3." (PMID 35497876, 2022). "It is necessary to testify the potential efficacy of SETDB1 suppression in more tumor models." (PMID 34294683, 2021). "Finally, SETDB1 silencing in BC cells inhibited tumor metastasis through regulation of Mothers against decapentaplegic homolog 7 (SMAD7) expression, which antagonized the transforming growth factor beta (TGF-β) pathway." (PMID 34440561, 2021). "Besides cytotoxic T cells, SETDB1 has been reported to play vital roles in other immune cells as well as tumor cells." (PMID 34294683, 2021). "Another study demonstrated that SETDB1 KO by CRISPR/CAS9 significantly increased the migration and transformation of the A549 cell line by regulating the expression of E-cadherin, ꞵ-catenin, STAT3, and AKT, which also indicates the tumour suppressive role of SETDB1." (PMID 34299035, 2021). "The authors discovered that Setdb1 was the top-ranked sensitizer in both models and Setdb1 deficiency robustly inhibited tumor growth in ICB treated rather than untreated mice." (PMID 34294683, 2021). "However, SETDB1 plays a different role in the non-invasive tumor mass vs. invasive front during TGF-β-induced signaling." (PMID 32114978, 2020). "Aberrant SETDB1 functionality and the related altered epigenetic changes have been shown to promote silencing of tumor suppressor genes, and thus contributes to enhance tumor growth and metastasis." (PMID 32471360, 2020). "However, some recent studies have shown that dysregulation of DNA methylation via aberrant SET Domain, Bifurcated 1 (SETDB1) gene expression can silence critical tumor suppressor genes and induce a more aggressive tumor phenotype in HNC." (PMID 31768101, 2019). "We next assessed the tumour growth rate in HCCLM3 xenograft model in nude mice on SETDB1 knockdown." (PMID 26471002, 2015). "In four out of the six pairs, SETDB1 expression is higher in tumour than in control." (PMID 26471002, 2015). "Despite advances in research, the full range of mechanisms through which this protein acts remains unclear; however, it is evident that SETDB1 has a pivotal role, particularly in the mesenchymal stem cells differentiation, tumor evasion and treatment resistance." (PMID 39945463, 2025). "Moreover, targeting H3K9me3 modulators (e.g., KDM4A or SETDB1) may activate anti-tumor immunity and enhance the efficacy of PD-1 blockade immunotherapy." (PMID 39519018, 2024). "Notably, we observed that SETDB1 was distinctly correlated with tumor immunity in MM." (PMID 35372573, 2022). "Finally, we observed that SETDB1 was distinctly correlated with tumor immunity in MM." (PMID 35372573, 2022). "Finally, in vivo experimental results revealed that SETDB1 silencing could impede CRC tumor growth in mice and immune cell infiltration via the FOSB/miR-22/BATF3/PD-L1 axis." (PMID 35497876, 2022). "Moreover, recent studies have shown that SETDB1 is a promising new target for tumor immunotherapy." (PMID 36077559, 2022).